IL1B (interleukin 1 beta)
Diseases named in the same sentence as IL1B in open-access papers (continued):
Sharing a sentence is not in itself a finding about the gene and the disease.
depression (continued). "Again, they found an increase in plasma levels of IL-1β, IL-6, and IL-17 in MDD MS patients (n=20) compared to MS patients without depression (n=20)." (PMID 36189272, 2022). "Pro-inflammatory cytokines, e.g., IL-1β, IL-6, TNF-α, and acute phase proteins, were described to be increased in experimental animal models of chronic stress-induced depression as well as in patients with major depressive disorder (MDD) compared to healthy controls." (PMID 36014842, 2022). "On the contrary, the more severe the depression, the lower the IFN‐γ levels, and similarly, although they were not significant, IL‐1β and IL‐12 presented the same pattern." (PMID 35588458, 2022). "In accordance with the findings, the IL-1β, TNF-α, and IL-6 levels in the group with depression exceeded those without depression, and the high level of IL-6 contributed to memory impairment in the depressive group." (PMID 34299040, 2021). "Hitherto, no meta-analysis has specifically compared the peripheral levels of proinflammatory markers including IL-1β, IL-6, TNF-α and CRP between elderly with depression or Alzheimer’s disease and controls without any psychiatric disorder." (PMID 30104698, 2018). "Rats with depression-like phenotype displayed increased levels of cytokines (IL-1β, IL-6, TNF-α, IL-4 and IL-10) in the PFC compared with sham-operated and rats without depression-like phenotype (P < 0.05) on day 21 after SNI surgery." (PMID 28600519, 2017). "In this study, we observed increased levels of proinflammatory cytokines of IL-6, IL-1β, TNF-α as well as anti-inflammatory cytokines of IL-4 and IL-10 in the rats with depression-like phenotype, but not rats without depression-like phenotype." (PMID 28600519, 2017). "In depressed females, but not depressed males, levels of IL-1β and TNF-α positively correlated with the severity of overall depression measured by the MADRS, and also with three individual items of the MADRS: lassitude, pessimism, and suicidal thoughts." (PMID 28670290, 2017). "Rats with depression-like phenotype displayed higher serum levels of IL-1β, IL-6 and TNF-α than rats without depression-like phenotype (P < 0.05)." (PMID 28600519, 2017). "Other studies have reported that serum IL-1β and TNF-α levels were not significantly higher in major depression disorders compared with normal subjects." (PMID 25237578, 2014). "Dysregulation of the HPA axis after MI and subsequent depression may be influenced by inflammatory factors, particularly Interleukin (IL)-12A and tumour necrosis factor (TNF)-α, but not IL-1β and IL-6." (PMID 41301929, 2025). "In this study, we revealed the significant differences in serum BDNF, GDNF, 5-HT, and IL-1β among the HC, PWE, and PWECD groups, along with the negative correlation with depression severity in serum GDNF and 5-HT levels, supporting their role in epilepsy and comorbid depression." (PMID 39474368, 2024). "In this study, we found that ketamine could attenuate decreased serum levels of IL-1β and IL-6, but not TNF-α level, in rats with depression-like phenotype." (PMID 28600519, 2017). "rTMS increased serum BDNF levels and decreased serum IL-1b and TNF-a levels inpatients with depression but had no effecton any of these factors in healthy individualsResults suggest that rTMS may increase BDNF and decrease IL-1b and TNF-a serum levels in elderly patients with refractory depression." (PMID 35735405, 2022). "Moreover, a rodent depression model, showed a lack of increased IL-1β but elevation of IL-6, similar to our results in the human DLPFC, strongly indicating that studies are required to identify how IL-1β level changes in the brain with ageing and its subsequent effects." (PMID 40179065, 2025). "This cytokine also affects the activity of the HPA axis by means of a negative feedback relationship between IL-1β production and overactivity of the HPA axis, whose dysregulation may play a role in initiating and maintaining the clinical and biochemical manifestations of depression." (PMID 33920992, 2021).
atherosclerosis (950 papers, 2007 to 2026). A disease characterized by the build-up of fatty material and calcium deposition in the arterial wall resulting in partial or complete occlusion of the arterial lumen. "Particularly, IL-1β is tightly linked to NLRP3 inflammasome activation in adipose tissue, endothelium, and vascular macrophages, and sustained IL-1β production has been implicated in atherosclerosis, type 2 diabetes, and functional decline in older adults." (PMID 41602164, 2026). "Elevated levels of IL-1β are closely associated with the progression of atherosclerosis and cardiac fibrosis." (PMID 41194915, 2025). "This, in turn, amplifies the production of IL-1β and IL-18—cytokines strongly associated with vascular inflammation, atherosclerosis, and plaque instability." (PMID 41154680, 2025). "Preclinical studies have shown that macrophages deficient in TET2 or DNMT3A drive interleukin (IL)-1β/IL-6 inflammasome activation, thereby promoting atherosclerosis and metabolic dysfunction, whereas the JAK2V617F mutation accelerates thrombosis." (PMID 41516113, 2025). "In Mtb-infected macrophages, an activated AhR pathway can induce the secretion of IL-1β, an important inflammatory cytokine associated with atherosclerosis." (PMID 40508196, 2025). "Interleukin-1 beta (IL-1β) plays a crucial role in the acute phase of stroke within the inflammatory cascade and serves as a long-term chronic contributor to atherosclerosis development and increased stroke risk." (PMID 41009650, 2025). "The protein encoded by the PRTN3 gene is one of the main components of neutrophils and is involved in the activation and processing of pro-inflammatory cytokines associated with atherosclerosis, such as IL-1β, TNF-α, and MCP-1." (PMID 39609876, 2024). "Monocytes of CKD patients express high levels of interleukin (IL)-1β and IL-1α, with IL-1β associated with an increased risk of atherosclerosis." (PMID 38416185, 2024). "In a mouse model of atherosclerosis induced by a high-fat diet, oral administration of GRb1 was found to suppress levels of inflammatory factors such as IL-1β, IL-6, and TNF-α in serum, attenuating apoptosis associated with inflammatory activity." (PMID 39339421, 2024). "This resulted in reduced transcription of IL-18 and IL-1β, prevention of foam cell pyroptosis, decreased release of DAMPs (damage-associated molecular patterns), all favorably contributing to inhibition of atherosclerosis progression." (PMID 38903990, 2024). "The activation and release of IL-1β by plaque macrophages are associated with chemotactic effects and increased foam cell formation, significantly promoting plaque inflammation and atherosclerosis." (PMID 39528464, 2024). "Corroborating all this, treatment with an anti-IL-1β antibody in patients with atherosclerosis was associated with significant reductions in reported cases of arthritis, gout and osteoarthritis, compared to those receiving a placebo." (PMID 39301197, 2024). "A gene susceptible to mutation in CHIP is Tet2, the dysfunction of which can also trigger the production of interleukin-1 beta (IL-1β), an inflammatory cytokine highly associated with atherosclerosis initiation." (PMID 39484071, 2024). "This activation leads to caspase-1-mediated maturation and secretion of IL-1β, further promoting the inflammatory response associated with atherosclerosis." (PMID 37900059, 2023). "Mice with experimental CHIP show increased pro-inflammatory drive of the NLRP3/IL-1β/IL-6 axis and atherosclerosis, and humans carrying a genetic deficiency in IL6 appear to have reduced cardiovascular risk related to CHIP." (PMID 37209535, 2023). "IL-1β, a pleiotropic cytokine implicated in the pathogenesis of atherosclerosis, was found to be significantly elevated in the atherogenic group compared to the control group." (PMID 37520489, 2023).
atherosclerosis (continued). "For instance, miR-467b has been implicated in the regulation of atherosclerosis and secretion of the proinflammatory cytokines IL-6, IL-1β, and TNF, which are also knowingly dysregulated in CCC." (PMID 36972298, 2023). "Tet2-deficient macrophages exhibit strong IL-1β secretion capacity and promote the formation and development of atherosclerosis in mice." (PMID 38012545, 2023). "Common to the human leukocytes studied and to the zebrafish larvae is the fact that ChA increases the proinflammatory cytokine IL-1β, a crucial cytokine implicated in the initiation and development of atherosclerosis." (PMID 37482218, 2023). "Previous studies showed, that TET2 or JAK2 clonal mutation increases IL-6 and IL-1β production in myeloid cells supporting accelerated atherosclerosis." (PMID 38138958, 2023). "IL-1α can be used as the target of treatment in atherosclerosis despite that a specific block of IL-1α predisposes patients to more severe infections compared with IL-1β inhibition." (PMID 37600028, 2023). "Several studies have implicated inflammasome-derived IL-1β and IL-18 in the development of atherosclerosis." (PMID 37443800, 2023). "Across studies TNF-α and IL-1β are correlated to the reduction in atherosclerosis-associated inflammation." (PMID 36904211, 2023). "recently found that macrophages express the olfactory receptor Olfr2 and all associated trafficking and signaling molecules, which drive atherosclerosis via NLRP3-dependent IL-1β secretion." (PMID 36911736, 2023). "Experimental studies showedthat atherosclerosis-prone mice deficient in IL-1β have smalleratherosclerotic plaques, and that atherosclerotic plaque increases in miceexposed to IL-1β." (PMID 39076864, 2023). "Considering a pathophysiologic point of view, among the inflammatory mediators, IL-1β seems to be one of the main cytokine involved in the complex network of immune-inflammation linked to atherosclerosis." (PMID 36768804, 2023). "In the context of CVD, the activation of the NLRP3 inflammasome in macrophages, with the consequent release of IL-1β, has been shown to be implicated in the development of atherosclerosis and the clinical manifestations of the disease." (PMID 36613465, 2022). "As the association between IL-1β and atherosclerosis has been highlighted, the benefits of targeting IL-1β has been emphasized in the past decades." (PMID 35563294, 2022). "In fact, NLRP3 inflammasome over-activation and the subsequent increase in inflammatory cytokines, especially IL-1β, has been frequently linked to atherosclerosis, diabetes, and related chronic sequels." (PMID 35204152, 2022). "IL-1B is one of the main proinflammatory cytokines capable of inducing changes in vascular SMC morphology associated with the progression of atherosclerosis." (PMID 35495944, 2022). "The clinical relevance of IL-1β in chronic inflammation underlying atherosclerosis has been reinforced by recent evidence associating pharmacological inhibition of the cytokine with lower cardiovascular risk." (PMID 35111374, 2022). "Previously, it has also been suggested that overexpression of IL-1β in the atherosclerotic plaque was associated with extensive atherosclerosis." (PMID 36555579, 2022). "IL-1β proteins bind to IL-1 receptors, and polymorphisms in IL-1β genes have been linked to atherosclerosis and acute myocardial infarction." (PMID 36035865, 2022). "Being involved in the DNA demethylation process, TET2 facilitates the suppression of IL-6 and IL-1β, inflammatory mediators implicated in the pathogenesis of atherosclerosis." (PMID 35663390, 2022).
atherosclerosis (continued). "The steps in this cascade contribute to the development of atherosclerosis 136, but the mechanism underlying hypercholesterolemia and IL-1β activity in the context of vascular calcification remains to be uncovered." (PMID 34803503, 2021). "In this regard, silencing IL-1β in apoE-deficient mice (ApoE−/−) that are susceptible to atherosclerosis has revealed a reduction in the rate and extent of coronary atherosclerosis." (PMID 32378144, 2021). "In this context, the demonstrated reduction of IL-18, IL-1β and IL-6 by colchicine make it a very attractive theoretical candidate for the reduction of inflammatory risk in atherosclerosis." (PMID 33970350, 2021). "Deficiencies in IL-1β and IL-18 reduced the lesion size in an apolipoprotein E-deficient mouse model of atherosclerosis." (PMID 33534121, 2021). "Secondary necrosis of apoptotic VSMCs promotes the release of both IL-1α and IL-1β, which induces the surrounding viable VSMCs to produce proinflammatory cytokines, thus causing a chronic inflammation associated with atherosclerosis." (PMID 35008765, 2021). "Statin therapy can down-regulate NLRP3, cathepsin-B, and downstream mediators such as IL-1β, which play a significant role in inflammation associated with atherosclerosis and reduce NLRP3 gene expression in PBMCs of CVD patients." (PMID 32378144, 2021). "Some reports stated that various extracts from PE cause inhibition of the production of TNF-α, IL-1β, and IL-6 in atherosclerosis or neuronal cellular model." (PMID 34712342, 2021). "The overexpression of the IL-1β receptor or exposure to IL-1β increases the progression of atherosclerosis, whereas knockdown of IL-1β or inhibition of IL-1β reduces the biomarkers and lesions associated with atherosclerosis in animal studies." (PMID 33071808, 2020). "In patients prone to development of atherosclerosis, polymorphism of the IL-1β gene cluster is associated with the extent of coronary arteries lesions, especially IL1B: −511 and −31 C/T polymorphism." (PMID 33371312, 2020). "IL-1β is the primary circulating form of IL-1 and then has been much focused; basic studies have shown that IL-1β deficiency decreases the severity of atherosclerosis." (PMID 33598482, 2020). "For example, a 2012 study showed that loss of TET2 function was associated with atherosclerosis and the increased secretion of pro-inflammatory factors including IL-1β." (PMID 32290079, 2020). "We also reviewed bench-to-bedside clinical translation of IL-1β neutralizing strategies associated with the use of IL-1β blockade in patients with atherosclerosis." (PMID 33362770, 2020). "Macrophages are the main source of IL-1β, which is responsible for inflammation linked to atherosclerosis." (PMID 33664731, 2020). "High expression levels of CD36 and LX-1 have been positively associated to the level of IL-1β, accelerating the progress of atherosclerosis while SR-A was negatively correlated with IL-8." (PMID 32733941, 2020). "We herein discussed the important immunomodulatory effect IL-1β exerts on atherosclerosis and the potential mechanisms underlying it." (PMID 33362770, 2020). "Compelling evidences indicate that HMGB1, TLR4, and IL-1β are implicated in the progression of atherosclerosis." (PMID 30881312, 2019). "The close association among free cholesterol, oxLDL macrophages, and IL-1β strongly support that cholesterol crystals are metabolic signals that trigger inflammation in atherosclerosis and NAFLD." (PMID 30983887, 2019). "IL-1β is a central mediator of inflammation that was implicated in the development of atherosclerosis and acute myocardial infarction." (PMID 31534437, 2019).
atherosclerosis (continued). "For example, IL-1β deficiency suppresses the progression of atherosclerosis and outward vascular remodeling in a murine model." (PMID 31735914, 2019). "Mechanistically, exacerbated IL-1β secretion by macrophages was proposed to be essential for accelerated atherosclerosis in context of CH due to Tet2 loss in mice." (PMID 30890702, 2019). "Knockout IL-1β in atherosclerosis-prone ApoE-deficient mice leads to attenuation of atherosclerosis development." (PMID 31534437, 2019). "The proposed mechanism for the link between clonal hematopoiesis and atherosclerosis involves increased NLRP3 inflammasome-mediated IL1β secretion in TET2-deficient macrophages in mice." (PMID 31712595, 2019). "In the context of TET2-mutation-positive CH, prophylactic treatment for atherosclerosis using cholesterol-lowering medications or compounds targeting IL-1β and other inflammatory pathways as proposed would, if effective, be a significant advance." (PMID 30890702, 2019). "Il1b (interleukin-1 beta) is a key pro-inflammatory cytokine that has been associated with the development of atherosclerosis and myocardial infarction." (PMID 31827539, 2019). "Genetic deficiency of IL-1 receptor 1 or treatment with anti-IL1β decreased atherosclerosis in the aortic sinus and total aorta of ApoE−/− mice." (PMID 31998318, 2019). "For example, IL-1β has long been implicated in the pathogenesis of both type 2 diabetes and atherosclerosis, and Canakinumab (anti-IL-1β-neutralising monoclonal antibody) is currently the focus of extensive clinical investigation for these indications." (PMID 31488830, 2019). "Blockage of the IL-1/IL-1R pathway can also be achieved with a neutralizing antibody directed against IL-1β, Canakinumab, which seems beneficial in atherosclerosis prevention in high-risk patients." (PMID 31507607, 2019). "Recently, the CANTOS trial confirmed the inflammatory theory of atherosclerosis and shed new light on the role of IL-1β in CV risk determination." (PMID 31652822, 2019). "For example, Tet2-deficient macrophages exhibit an increase in inflammasome-mediated IL-1β secretion, which is associated with accelerated development of atherosclerosis in these mice." (PMID 29946544, 2018). "In terms of CVD prevention, canakinumab was particularly attractive since known atherosclerosis risk factors upregulate IL-1β via the NLRP3 inflammasome." (PMID 29922680, 2018). "IL-1β has been shown to be implicated in the pathogenesis of atherosclerosis and thrombosis by the downstream stimulation of IL-6 and C-reactive protein (CRP)." (PMID 30333009, 2018). "In the recent trial of anti-IL-1β antibody in a large population of high risk atherosclerosis patients (CANTOS), the intervention reduced inflammation and cardiovascular events." (PMID 30618774, 2018). "This interaction leads to the secretion of IL-1β and IL-18, which have been associated with atherosclerosis severity." (PMID 30558209, 2018). "Particularly relevant to our findings, IL1b mRNA levels are decreased in perforin or granzyme B deficient mice compared to WT mice in a mouse model of atherosclerosis." (PMID 28192528, 2017). "Macrophage-associated cytokines such as TNF-α, IL-1β, and IL-6 have emerged as key factors in the pathogenesis of atherosclerosis." (PMID 27281478, 2016). "Atherosclerosis-prone mice that are deficient in IL-1β develop smaller lesions, and administration of IL-1RA reduces early atherogenesis in mice." (PMID 27737744, 2016). "Studies in mouse models of atherosclerosis have shown a reduced atherosclerotic burden in IL-1β-deficient animals." (PMID 26114549, 2015). "In animal models, IL17A deficiency was observed to reduce atherosclerosis, decrease the number of macrophages in the atheroma, and inhibit release of monocyte chemoattractant protein 1, IL1b, IL12, and interferon gamma in the plaque." (PMID 28352449, 2014).